TYMS (thymidylate synthetase)
Description:
Catalyzes the reductive methylation of 2'-deoxyuridine 5'-monophosphate (dUMP) to thymidine 5'-monophosphate (dTMP), using the cosubstrate, 5,10-methylenetetrahydrofolate (CH2H4folate) as a 1-carbon donor and reductant and contributes to the mitochondrial and nuclear de novo thymidylate biosynthesis pathway.
Synonyms: TS; TSase; TMS; HsT422; DKCD
Tractability: Small molecule: an approved drug acts on it; a structure with a bound ligand is known; a high-quality ligand is known; it has a high-quality binding pocket; it belongs to a druggable protein family. PROTAC: UniProt records ubiquitination sites on it; ubiquitination databases record sites on it; a small molecule that binds it is known.
Target class: Enzyme; Transferase
Chemical probes: CB-3717, CHEMBL25889, OSI-7904, PD080999, PD081688, PD081703, PD081727, PD081979, PD082231, PD082257, PD082291, PD082939, PD082979, PD083056, PD083161, PD083440, PD083448, PD083958, PD083998, PD084504, and 1 more
Safety:
Unwanted effects reported when the protein is acted on. In parentheses: how it was acted on, where the effect was seen, and who reports it.
asthenia (source: ClinPGx)
diarrhea (source: ClinPGx)
discontinuation of therapy due to severe toxicity (source: ClinPGx)
drug toxicity (source: ClinPGx)
nausea and vomiting (source: ClinPGx)
side effects (source: ClinPGx)
Gene: Protein-coding gene on chromosome 18 (657,515 to 676,613, forward strand). Ensembl gene ENSG00000176890.
Subcellular location: Nucleus; Cytoplasm; Mitochondrion; Mitochondrion matrix; Mitochondrion inner membrane
Pathways (Reactome):
Cell Cycle: G1/S-Specific Transcription
Metabolism: Interconversion of nucleotide di- and triphosphates
Gene Ontology:
Molecular function: mRNA regulatory element binding translation repressor activity; protein binding; sequence-specific mRNA binding; thymidylate synthase activity; folic acid binding; transferase activity, transferring one-carbon groups
Biological process: 'de novo' pyrimidine nucleobase biosynthetic process; DNA replication; dTMP biosynthetic process; negative regulation of translation; tetrahydrofolate interconversion; DNA biosynthetic process; dTTP biosynthetic process
Cellular component: cytoplasm; mitochondrial inner membrane; mitochondrial matrix; mitochondrion; nucleus; replication fork; cytosol
Genetic constraint (gnomAD): Loss-of-function variants: 19 observed, 31.59 expected, observed/expected ratio (o/e) 0.6, 90% interval 0.42 to 0.88. The upper end of that interval is the gene's LOEUF score, 0.88, which puts it in group 3 of 6, group 1 being the genes least tolerant of losing a copy. Missense variants: 260 observed, 339.24 expected, observed/expected ratio (o/e) 0.77, 90% interval 0.69 to 0.85. Synonymous variants: 163 observed, 133.69 expected, observed/expected ratio (o/e) 1.22, 90% interval 1.07 to 1.39.
Homologues: Orthologues: chimpanzee TYMS (99% identical), macaque TYMS (98% identical), pig TYMS (94% identical), rabbit TYMS (92% identical), mouse Tyms (89% identical), dog TYMS (88% identical), rat Tyms (88% identical), guinea pig TYMS (87% identical), tropical clawed frog tyms (78% identical), zebrafish tyms (76% identical), Drosophila melanogaster Ts (63% identical), Caenorhabditis elegans tyms-1 (62% identical). Paralogues in human: DHFR (15% identical), DHFR2 (14% identical).
Diseases named in the same sentence as TYMS in open-access papers:
TYMS is named in the same sentence as 188 diseases in open-access papers, as found by Europe PMC text mining. Sharing a sentence is not in itself a finding about the gene and the disease. The quoted sentences say what the papers report.
colorectal cancer (117 papers, 1988 to 2025). A primary or metastatic malignant neoplasm that affects the colon or rectum. "There is evidence that TYMS up-regulation is associated with adverse clinical behavior in a variety of solid tumor types, such as lung, breast, gastric, and colorectal cancer." (PMID 37373974, 2023). "The reason for the resistance to folate-related antimetabolites is seen in thymidylate synthase (TYMS), whose overexpression has been observed in several solid tumors, including tumors associated with breast cancer, colorectal cancer and mesothelioma." (PMID 37894370, 2023). "In this context, it has been associated with response to chemotherapy for colorectal cancer in a Mexican cohort, highlighting the importance of TYMS to cancer treatment in Latin American populations." (PMID 35678683, 2022). "TYMS was associated with the prognosis of colorectal cancer patients, and high expression of TYMS was markedly associated with lower survival rate in colorectal cancer patients." (PMID 34141464, 2021). "High expression of Thymidylate synthetase (TYMS) is associated with resistance to TYMS targeted drugs such as 5-fluorouracil in colorectal cancer." (PMID 34141464, 2021). "TYMS encodes thymidylate synthase, which is the primary target of 5-FU, impairs the drug sensitivity in colorectal carcinoma, and is found to activate aggressive cancer cells." (PMID 35071232, 2021). "The results of this study therefore strongly suggest a potential importance of the XRCC3-Thr241Met and TYMS-VNTR polymorphisms in relation to time-to-metastasis in colorectal cancer." (PMID 29394274, 2018). "TYMS polymorphisms are among the most studied variants in colorectal cancer due to the function of the encoded protein." (PMID 29394274, 2018). "Many studies were performed to investigate the relation between mutations/polymorphisms of coding region of TYMS and various diseases, such as colorectal cancer, lymphoma and acute lymphocytic leukemia." (PMID 22384047, 2012). "The aim of our work was to evaluate the clinical outcome and toxicity of colorectal cancer patients on adjuvant treatment with 5FU in relation with demographic characteristics, known TYMS and MTHFR polymorphisms, and individual 5FU CL." (PMID 19384296, 2009). "The association between high levels of TYMS in tumours and poor clinical response following 5-FU treatment of colorectal cancer is well documented." (PMID 15655543, 2005). "Moreover, resistance to 5-fluorouracil (5-FU) in colorectal cancer has been linked to the overexpression of thymidylate synthase (TYMS) and increased dUTPase activity, which together drive competitive inhibition of the drug’s molecular target." (PMID 41229498, 2025). "MSI-H has been associated with right-sided colorectal cancer and an immune-active tumor microenvironment, suggesting that high tumor TYMS expression and MSI-H may collectively indicate heightened immune activity within the tumor microenvironment." (PMID 39998667, 2025). "Cancers with a proficient MMR system, however, comprise the majority (80% to 85%) of colorectal cancers and adjuvant therapy decision in such patients should be addressed to other factors, for instance TYMS expression, which we found associated to therapy benefit in patients with pMMR tumours." (PMID 23446022, 2013). "Contradictory results have been reported regarding the relationship between TYMS expression and prognosis in patients with colorectal cancer." (PMID 39998667, 2025). "TYMS has been reported to be an oncogene for colorectal cancer, pancreatic cancer and lymphoma and promotes tumor progression, but its role in LUAD has rarely been reported." (PMID 40642061, 2025). "In HPV(+) HNSCC patients, higher TYMS expression correlates with a poorer response to 5-FU treatment than was noted in the case of colorectal cancer." (PMID 40299341, 2025). "TYMS, involved in nucleotide biosynthesis and DNA repair, is overexpressed in metastatic breast, lung adenocarcinoma, and colorectal cancers." (PMID 41244050, 2025).
colorectal cancer (continued). "The long non-coding RNA SNHG15 promotes TYMS expression, leading to colorectal cancer resistance to 5-FU chemotherapeutic agents." (PMID 39353904, 2024). "TYMS is highly expressed in patients with colorectal cancer and non-small cell lung cancer, and patients with lower TYMS mRNA levels have higher survival rates than those with higher expression." (PMID 36874006, 2023). "TYMS is expressed in almost all tumor cells, and more TYMS is found in non-small cell lung cancer, colorectal cancer, breast cancer, and cholangiocarcinoma." (PMID 37682862, 2023). "In a previous work, we have demonstrated that SFRE inhibited thymidine kinase 1 (TK1) and thymidylate synthase (TYMS) synergising with 5- fluorouracil (5-FU) in the inhibition of colorectal cancer cell lines proliferation." (PMID 36439419, 2022). "The expression level of TYMS in colorectal cancer patients was significantly higher than that in normal control group." (PMID 36532716, 2022). "For colorectal cancer module, the analysis revealed the occurrence of approved drug targets TYMS, TOP1, BRAF and EGFR." (PMID 35053185, 2021). "Thymidylate synthase (TYMS) and UGT1A germline polymorphisms influence the therapeutic outcome of colorectal cancer (CRC) patients treated with irinotecan plus 5-fluorouracil (irinotecan/5FU)." (PMID 34948113, 2021). "In order to reveal the potential function of TYMS in colorectal cancer and its regulatory network in more detail, we conducted bioinformatics analysis of public sequencing data to guide future studies of colorectal cancer." (PMID 34141464, 2021). "We collected clinical samples to verify the expressions of TYMS and BCL2L1 in colorectal cancer and results of TYMS was consistent with the result of TCGA and GEO analysis." (PMID 34141464, 2021). "The qRT-PCR verification results indicated that expression of TYMS was up-regulated in colorectal cancer tissues compared with adjacent normal tissues." (PMID 34141464, 2021). "TYMS and BCL2L1 were associated with the prognosis of colorectal cancer patients, which was consistent with previous reports of TYMS and BCL2L1 in other cancers." (PMID 34141464, 2021). "In colorectal cancer, knockdown of TYMS can inhibit tumor cell proliferation and promote cell apoptosis." (PMID 35003215, 2021). "TYMS was identified as a biomarker for hepatocellular carcinoma liver transplantation, pancreatic and colorectal cancer." (PMID 33519918, 2020). "Melatonin represses 5-FU resistant colorectal cancer cell growth via miR-215-p/thymidylate synthase (TYMS) pathway." (PMID 33344223, 2020). "Initially, we profiled the expression of FOXM1 and TYMS in colorectal cancer cell lines, and also measured the expression of E2F1 as it is known to regulate TYMS and FOXM1 expression, independently." (PMID 30728402, 2019). "Increased TYMS expression is thought to be responsible for 5-FU resistance in patients with colorectal cancer." (PMID 31247977, 2019). "Our main finding is that specific genotypes of two common polymorphisms, XRCC3-Thr241Met and TYMS-5’ UTR VNTR, were significantly associated with early metastasis in colorectal cancer." (PMID 29394274, 2018). "The aim of this study was to investigate the effect of dihydropyrimidine dehydrogenase (DPYD), thymidylate synthase (TYMS), and methylenetetrahydrofolate reductase (MTHFR) polymorphisms in colorectal cancer patients." (PMID 30551678, 2018). "In conclusion, we have identified two polymorphisms, XRCC3-Thr241Met and TYMS 5’ UTR VNTR, whose specific genotypes are significantly associated with early metastasis in colorectal cancer." (PMID 29394274, 2018).
colorectal cancer (continued). "Our subsequent studies demonstrated that these miRNAs have direct functional significance in colorectal cancer by regulating key targets such as thymidylate synthase (TYMS, TS), dihydrofolate reductase (DHFR), histone deacetylase, E2F3, and Bcl-2." (PMID 28881738, 2017). "Capecitabine, a fluoropyrimidine prodrug, has been a frequently chosen ligand for the last one and half decades to inhibit thymidylate synthase (TYMS) for treatment of colorectal cancer." (PMID 27026843, 2016). "Recent studies have shown that overexpression of TYMS transcript predicts poor outcome in colorectal cancer patients." (PMID 27733154, 2016). "We evaluated the association between nine polymorphisms in MTHFR, CDA, TYMS, ABCB1, and ENOSF1 and adverse reactions, dose reductions, treatment delays, and overall toxicity in 239 colorectal cancer patients treated with capecitabine-based regimens." (PMID 25691056, 2015). "Further, the measurement of thymidylate synthetase mRNA in primary colorectal cancer can reflect those in synchronous liver metastases." (PMID 23300952, 2013). "In another study, miR-192 and miR-215 were identified as post-transcriptional regulators of TYMS, a predictive biomarker for 5-FU response in colorectal cancer." (PMID 23965981, 2013). "The impact of thymidylate synthase (TYMS) and UDP-glucoronosyltransferase 1A (UGT1A) germline polymorphisms on the outcome of colorectal cancer (CRC) patients treated with irinotecan plus 5-fluorouracil (irinotecan/5FU) is still controversial." (PMID 20628391, 2010). "We hypothesized that the overexpression of TYMS may enhance the antioxidant capacity of colorectal cancer (CRC) cells by facilitating the nuclear translocation of NRF2, thereby strengthening the resistance of CRC cells to ferroptosis." (PMID 39744483, 2025). "We identified the biological effect and molecular mechanisms of TYMS in colorectal cancer (CRC)." (PMID 39744483, 2025). "Raltitrexed works by inhibiting TYMS and is primarily used in advanced colorectal cancer." (PMID 39273288, 2024). "Initial studies have indicated that reducing TYMS expression may increase sensitivity to 5-FU chemotherapy in colorectal cancer patients." (PMID 39353904, 2024). "In addition, 5-fluorouracil (5-FU) specifically targets TYMS and is commonly used as a primary chemotherapy option for colorectal cancer, typically resulting in response rates of around 60–65%." (PMID 39273288, 2024). "However, in other clinical studies of breast cancer, lung cancer, and colorectal cancer, patients with low TYMS expression showed better chemotherapy response and higher survival rates." (PMID 35204496, 2022). "Although a large number of studies have focused on the association of TYMS with carcinogenesis, prognosis, chemotherapy reaction in colorectal cancer, ovarian cancer, pancreatic cancer, cervical cancer, and breast cancer, few studies focused on the role of TYMS in metastatic HCC patients." (PMID 34858842, 2021). "TYMS was altered in 16 of 524 (3.05%) colorectal cancer patients." (PMID 34141464, 2021). "We previously observed association of TYMS polymorphisms with the methylation levels of tumor suppressor and DNA repair genes in colorectal cancer cells, but no previous study investigated the contribution of TYMS polymorphisms to MTHFR gene methylation." (PMID 31370354, 2019). "However, despite being analyzed in multiple studies, the TYMS VNTR genotype–prognosis link in colorectal cancer remains inconclusive." (PMID 29394274, 2018). "The evidence supporting the predictive role of gene/protein expression of TYMS–5FU/Capecitabine in colorectal cancers, TUBB3-taxanes in NSCLC and MGMT–temozolomide in brain tumors was modest and mainly from level III observational studies and level IV pre-clinical studies." (PMID 27888622, 2017). "TYMS is considered as a potential prognostic marker for colorectal cancer." (PMID 27733154, 2016).
colorectal cancer (continued). "Moreover, HSP90-targeting small molecule inhibitor, ganetespib, was shown to downregulate TYMS, thus sensitizing colorectal cancer cell line to 5-FU." (PMID 26416450, 2015). "TYMS expression is reported to be regulated by miR-192 and miR-215 in colorectal cancer cell lines." (PMID 23915286, 2013). "Thus, in the light of our and others findings, it is plausible to suggest that the 3R VNTR genotype of TYMS could have a direct biological role in accelerating disease progression/metastasis in colorectal cancer." (PMID 29394274, 2018). "In addition, MTHFD2 expression was associated with prognosis of colorectal cancer and lung adenocarcinoma; however, TYMS expression was not." (PMID 30582043, 2018). "The most extensively reported TYMS variants are two insertion/deletion sites in 5′UTR (rs34743033) and 3′UTR (rs34489327), respectively, which are associated with the occurrence of various tumors, such as colorectal cancer, lymphoma, and acute lymphocytic leukemia." (PMID 22384047, 2012). "High expression of nucleotide synthetic enzyme thymidylate synthase (TYMS) is responsible for the resistance to fluorouracil (FU) treatment and worse survival in colorectal cancer (CRC)." (PMID 40682666, 2025). "Next to targeting DHFR, the one-carbon cycle is inhibited by drugs directed at thymidylate synthase (TYMS), like 5-fluorouracil (5-FU), which is used as first-line therapy for colorectal cancer (CRC)." (PMID 37591722, 2023). "The purpose of this study was to study the role of thymidylate synthetase (TYMS) and B-cell lymphoma-2 like 1 (BCL2L1) in the occurrence and development of colorectal cancer and its potential regulatory mechanism." (PMID 34141464, 2021). "The expression level of TYMS and BCL2L1 were significantly elevated in colorectal cancer patients than normal control." (PMID 34141464, 2021). "In TCGA and GEO, TYMS and BCL2L1 were significantly up-regulated and exhibited a moderately prognostic value for colorectal cancer.." (PMID 34141464, 2021). "We carried out the cBioPortal to determine the types and frequency of TYMS and BCL2L1 alterations in in colorectal cancer according to sequencing data from TCGA database." (PMID 34141464, 2021). "The Cancer Genome Atlas (TCGA) and Gene Expression Omnibus (GEO) were analyzed to examine the expression and prognostic value of TYMS and BCL2L1 in colorectal cancer." (PMID 34141464, 2021). "In human colorectal cancer tissue specimens, a strong correlation of FOXM1 and TYMS staining was observed." (PMID 30728402, 2019). "The expression vector carrying the Kozak-modified TYMS cDNA, pTRE2hyg-TS3, and pTet-ON/OFF vectors were co-transfected into a human colorectal cancer cell line, DLD-1." (PMID 25881233, 2015). "The enzyme thymidylate synthase (TS) and its coding gene (TYMS) are prognostic markers of the effectiveness of treatment with antifolates for several malignancies in humans, such as colorectal cancer." (PMID 40872698, 2025).